ALB (albumin)
Diseases named in the same sentence as ALB in open-access papers (continued):
Sharing a sentence is not in itself a finding about the gene and the disease.
cardiovascular disease (continued). "This study was conducted to explore the associations between serum albumin and markers of inflammation and cardiovascular disease in treated human immunodeficiency virus (HIV)-infected adults." (PMID 30515432, 2018). "Estimated glomerular filtration rate (eGFR) and urine albumin-to-creatinine ratio (UACR) are renal markers associated with risks of cardiovascular diseases (CVD) and all-cause mortality in diabetic patients." (PMID 28152985, 2017). "In contrast, this polymorphism was protective against albumin excretion and cardiovascular disease in type 1 diabetic Finnish patients." (PMID 27114872, 2016). "Studies conducted over the past decades have provided substantial evidence that increased urinary albumin excretion is a risk factor for diabetic nephropathy and cardiovascular diseases." (PMID 26607500, 2015). "The serum levels of creatinine, cystatin C, and urinary albumin excretion which are factors significantly associated with cardiovascular disease were evaluated as indicators of kidney function." (PMID 24678413, 2014). "Other factors that were not analyzed in this study but that play a role in adverse outcomes associated with hepatobiliary surgery include low serum albumin, low serum creatinine, and cardiovascular disease." (PMID 25032044, 2014). "Urinary albumin excretion is known to be independently associated with progression of renal and cardiovascular disease." (PMID 23723966, 2013). "In conclusion, we showed that cardiovascular disease, prior catheter use, levels of albumin, hsCRP, and fetuin-A were associated with primary patency loss in both patients with a fistula and a graft." (PMID 23557085, 2013). "Cardiovascular disease, prior catheter use, albumin, hsCRP, and fetuin-A are risk factors for patency loss." (PMID 23557085, 2013). "Regarding donor vigilance, the relatively low level of albumin in Group IV indicates that donors with an undiagnosed cardiovascular disorder, or at risk of developing one, should be rejected as high-frequency, high-volume donors to avoid oedema." (PMID 20840337, 2010). "Studies have shown an association between ALB and cardiovascular disease, as albumin exhibits protective effects against inflammation and oxidative stress on vascular endothelial function and inhibits platelet-activating factors, counteracting platelet aggregation." (PMID 41327740, 2025). "Patients who exhibit decreased serum albumin levels may be susceptible to cardiovascular disease, even when their levels are within the normal range." (PMID 40290308, 2025). "Notably, both BUN and serum albumin levels have been independently linked to adverse outcomes in patients with cardiovascular disease." (PMID 40806817, 2025). "Studies have shown that low albumin levels are associated with increased all-cause mortality and may further elevate the risk of cardiovascular disease by enhancing oxidative stress and endothelial damage." (PMID 39980677, 2025). "Even within the normal range, patients with decreased serum albumin concentration may be at risk of cardiovascular disease." (PMID 40929100, 2025). "A longitudinal study by Schalk showed that older adults with decreased serum albumin concentrations, even within the normal range, may be at increased risk for cardiovascular disease." (PMID 38779492, 2024). "Consequently, abnormally low serum albumin levels can lead to increased risk of cardiovascular disease and toxicity of drugs that have narrow therapeutic indices." (PMID 38713534, 2024). "In addition, an increase in albumin levels has been shown to reduce oxidative stress, which is a risk factor for unconventional cardiovascular disease." (PMID 36762995, 2023). "The assumption of the antioxidative and anti-inflammatory properties of albumin may remain biologically plausible and circulating albumin has also been observed to have an inverse association with the risk of cardiovascular disease morbidity and mortality." (PMID 37441531, 2023).
cardiovascular disease (continued). "This is unsurprising, since height loss beginning in middle age was previously found to be associated with high subsequent mortality due to cardiovascular disease, and low serum albumin levels were reported to be associated with high mortality due to cardiovascular disease." (PMID 37700384, 2023). "Many previous studies have shown that hs-CRP is strongly associated with a higher incidence of long-term ischemic events in patients with CAD treated with PCI, and decreased serum albumin is associated with susceptibility and poor prognosis of cardiovascular disease." (PMID 36747210, 2023). "Furthermore, albumin and BMI were negatively associated with the risk of impaired PF; while lesion number ≥ 3, cardiovascular disease, male, and respiratory disease increased the risk of impaired PF." (PMID 37076819, 2023). "In fact, angiogenesis inhibitor therapies might be associated with an increased incidence of cardiovascular disease, which was previously shown to be the case with low serum albumin levels." (PMID 37700384, 2023). "Since low serum albumin levels are reported to be associated with high mortality caused by cardiovascular disease, they may also contribute to height loss." (PMID 37700384, 2023). "Elevated levels of C-reactive protein (CRP) and urinary albumin-to-creatinine ratio were independently associated with ADL disability among older adults with cardiovascular disease, and subjects with higher levels of both markers had a more unfavorable metabolic profile than those with lower levels." (PMID 36003971, 2022). "An early study reported that the total cholesterol to albumin ratio could be used as an alternative parameter in predicting the risk of cardiovascular disease in 30 patients with a history of cardiovascular disease, with 5.0 as a cutoff value." (PMID 35755025, 2022). "Lower serum albumin was associated with fracture, an association reported previously in a cohort with underlying cardiovascular disease, and may represent compromised nutritional status or an increased inflammatory status." (PMID 35677742, 2022). "An early study reported that the total cholesterol to albumin ratio could be used as an alternative parameter in predicting the risk of cardiovascular disease in the general population." (PMID 35755025, 2022). "Association of albumin levels and cardiovascular disease (CVD) mortality in the COX model." (PMID 36523355, 2022). "In addition, hepatic rSO2 levels were independently associated with BMI, Hb levels, a history of cardiovascular disease, the mean BP, the serum albumin concentration, and the COP on the multivariable linear regression analysis." (PMID 34673824, 2021). "Serum FABP4, age, and albumin remained significantly associated with the AAC score in PD patients after adjustment for the history of cardiovascular disease, systolic BP, diastolic BP, residual kidney Kt/V, serum corrected calcium, us-CRP, TG, HDL-C, skeletal muscle mass, and body fat mass." (PMID 34789046, 2021). "In a research paper from the Framingham heart study cohort, low albumin level(s) in the urine (less than 30 mcg) was associated with increased risk of cardiovascular disease and death, even after adjustment of other important risk factors in the nondiabetic nonhypertensive population." (PMID 34847294, 2021). "These latter conditions may worsen the drop in albuminemia observed in the severe disease, since low serum albumin levels are independently linked to several cardiovascular diseases." (PMID 33956870, 2021). "Our multivariable LR models based on the baseline, 6-month and 12-month datasets further confirmed that an older age combined with cardiovascular disease, lower serum albumin levels, and higher LDL-c levels were independent risk factors for premature mortality in patients receiving PD." (PMID 33988129, 2021). "Furthermore, we investigated the urinary albumin excretion, which can also be a risk factor for cardiovascular disease." (PMID 32427855, 2020).
cardiovascular disease (continued). "Early detection of Microalbuminuria/Moderate albumin excretion in asymptomatic patients, can be beneficial in leading to complicated cardiovascular diseases and may be helpful by early diagnosis of this high risk disease." (PMID 32292459, 2020). "Moreover, even moderately increased levels of urinary albumin excretion (measured by a spot urinary albumin to creatine ratio test (UACR)) correlate with elevated risk for cardiovascular disease (CVD)." (PMID 32539802, 2020). "Serum albumin is a significant risk factor for cardiovascular disease in CKD patients." (PMID 30617956, 2019). "The ratio of arginine and lysine was higher in globulin than albumin and glutelin, indicating a better nutritional property of globulin because a high arginine to lysine ratio may reduce the risk of cardiovascular disease." (PMID 29439533, 2018). "This association suggests that an approach of reducing urinary albumin could be used to prevent cardiovascular disease, which is a leading cause of death." (PMID 23830507, 2013). "The establishment of an association between urinary excretion of albumin and cardiovascular morbidity and mortality in the general population may support the measurement of urinary albumin as a cardiovascular disease marker." (PMID 23830507, 2013). "In this prospective cohort study of 919 incident hemodialysis patients with an arteriovenous access, we showed that cardiovascular disease, prior catheter use, levels of albumin, hsCRP, and fetuin-A were associated with primary patency loss in both patients with a fistula and a graft." (PMID 23557085, 2013). "However, the specific causal relationship between serum albumin levels and cardiovascular disease remains partially unknown." (PMID 38580915, 2024). "In addition, albumin is an essential protein that binds and transports various drugs and substances to maintain venous oncotic pressure and influences the circulatory system, and a decreased albumin level has been shown to serve as a strong predictor of an increased risk for cardiovascular disease." (PMID 39517408, 2024). "Whilst some additional factors such as a history of cardiovascular disease and lower serum albumin levels are associated with fracture, incorporating them into models built on alternative pathophysiology hypotheses does not meaningfully improve the ability to predict fracture." (PMID 35677742, 2022). "Compared with young and middle-aged patients, elderly patients were more likely to be complicated with underlying diseases such as cardiovascular disease, abnormal liver, and kidney function, and these basic diseases may cause patients’ albumin levels to be lower than normal." (PMID 34526075, 2021). "Higher urine albumin excretion is associated with elevated hs-cTnT among persons without clinically evident cardiovascular disease, suggesting that albuminuria may be a potential risk factor for subclinical cardiovascular disease in the general population." (PMID 26301504, 2015). "In particular, the lower albumin level in the US source plasma donors (Group IV) might result in a lower osmotic pressure leading possibly to oedema in older donors, donors with an undiagnosed cardiovascular disorder, or donors at risk of developing one." (PMID 20840337, 2010). "The Prognostic Nutritional Index (PNI), which reflects the immunonutritional and inflammatory status through serum albumin concentration and lymphocyte count, has emerged as a reliable prognostic indicator in cardiovascular disease." (PMID 41598492, 2026). "An increasing number of studies find uric acid to albumin ratio (UAR) plays an important role in predicting prognosis of cardiovascular disease." (PMID 41602990, 2026). "Blood glucose and serum albumin can be biomarkers at admission since they are easily accessible and demonstrate correlations with cardiovascular diseases." (PMID 40351679, 2025).
cardiovascular disease (continued). "Prolonged hospital stays were related to cardiovascular disease, chronic renal disease, peripheral blood sCRP, albumin and use of glucocorticoid at admission." (PMID 40033231, 2025). "Fibrinogen-to-albumin ratio (FAR) is significantly associated with the severity and prognosis of cardiovascular disease (CVD)." (PMID 40510491, 2025). "Sensitivity analysis 2 included additional adjustments for total bilirubin, creatinine, albumin, uric acid, systemic immune-inflammation index, and history of cardiovascular disease." (PMID 40060378, 2025). "The nomogram model constructed with internal iliac artery calcification, serum albumin level, age, and comorbid cardiovascular disease was well discriminative, calibrated, and clinically applicable for predicting 3-year survival." (PMID 39763079, 2025). "Previous studies have demonstrated that the PNI, a composite of serum albumin and total lymphocyte count, is a robust predictor of adverse outcomes across a broad spectrum of cardiovascular diseases." (PMID 41272173, 2025). "It is well established that low serum albumin levels reflect the severity of inflammation and contribute to the progression of cardiovascular diseases (CVDs)." (PMID 41048521, 2025). "Adjusted for time-weighted average ­HbA1c, age, sex, cardiovascular disease history, BMI, hemoglobin, albumin and C-reactive protein." (PMID 41282290, 2025). "Albumin level is an established prognostic marker in a wide range of conditions, including cardiovascular disorders." (PMID 41488456, 2025). "The nomogram predicting the prognosis included IIAC, serum albumin level, age, and comorbid cardiovascular disease." (PMID 39763079, 2025). "The purpose of this study was to investigate the association between red blood cell distribution width and albumin ratio (RAR) and cardiovascular disease (CVD) and to determine the relevant thresholds." (PMID 41366972, 2025). "Serum albumin’s prognostic value for cerebrovascular and cardiovascular diseases is restricted by its sensitivity to a variety of factors, including liver function, catabolism, and extravascular leakage." (PMID 40290308, 2025). "The neutrophil-percentage-to-albumin ratio (NPAR) is a new marker used in the detection of cardiovascular diseases (CVDs)." (PMID 40428737, 2025). "The CONUT score, which evaluates albumin, total cholesterol (TC), and lymphocyte count, is widely used to assess nutritional status in cardiovascular diseases." (PMID 40777566, 2025). "Albumin is synthesized in the liver and plays a protective role in cardiovascular diseases by exerting anti-inflammatory, anti-oxidative stress, anti-platelet aggregation, and anticoagulant effects." (PMID 41245592, 2025). "The neutrophil/albumin ratio (NAR) is a novel promising biomarker in assessing cardiovascular disease severity." (PMID 40870540, 2025). "Red blood cell distribution width (RDW) and albumin separately have been used as mortality predictors for people with cardiovascular disease (CVD)." (PMID 40890156, 2025). "Reduced serum albumin levels resulting in elevated BAR indicate poor nutritional status, a risk factor for cardiovascular disease." (PMID 40290308, 2025). "Beyond serving as an indicator of nutritional status and hepatic synthetic function, albumin is intricately involved in the pathophysiology of cardiovascular diseases." (PMID 41245592, 2025). "ICU mortality, CRRT need, mechanical ventilation on admission, age, APACHE II score, SOFA score, and Charlson comorbidity index, as well as the presence of cardiovascular disease, were significantly different across the lactate/albumin ratio quartiles." (PMID 39685564, 2024). "Numerous observational studies have also highlighted the predictive and prognostic value of albumin in cardiovascular diseases." (PMID 38402549, 2024). "Uric acid/albumin ratio (UAR) is a novel composite biomarker with superior predictive value for cardiovascular disease." (PMID 38269629, 2024).
cardiovascular disease (continued). "Compared who did not develop PPCs, those who developed PPCs were more likely to be older, had more cardiovascular diseases and lower albumin, and underwent more thoracotomy." (PMID 38480929, 2024). "Multiple studies have revealed that lactate and albumin can serve as prognostic and mortality predictors for cardiovascular diseases." (PMID 39624213, 2024). "At the same time, it will also help us to more fully understand the important role of serum albumin in cardiovascular disease, laying a solid foundation for the development of new treatment strategies and methods." (PMID 38655495, 2024). "It is clear, however, that sACR is an index composed of two important prognostic factors for cardiovascular disease: serum albumin, which is related to liver function, and serum creatinine, which is related to kidney function." (PMID 39027002, 2024). "Significant interactions were found between the lactate/albumin ratio and sex, as well as between the lactate/albumin ratio and cardiovascular disease in the subgroup analyses (all p for interaction < 0.05)." (PMID 39685564, 2024). "An increasing body of evidence suggests that serum albumin levels play a role in cardiovascular diseases." (PMID 38580915, 2024). "A very large body of evidence supports the prognostic role of serum albumin levels in cardiovascular disease, abdominal surgical disease, orthopedic disease, gynecological disease, and infectious disease." (PMID 38500655, 2024). "Serum albumin level is used as a marker for several diseases including renal, hepatic and cardiovascular disorders." (PMID 38741158, 2024). "The nomogram model included eight independent predictors: age, sex, education status, marital status, smoking, serum albumin, blood urea nitrogen, and previous cardiovascular disease." (PMID 38577011, 2024). "Although both plasma lactate and albumin have a connection to cardiovascular disease, previous studies demonstrated limited evidence about those systemic inflammatory biomarkers alone examining this reciprocal relationship to prognosis of AMI." (PMID 37730950, 2023). "Albumin is a marker of nutrition, frailty, and inflammation, all of which have been individually reported to contribute to the cardiovascular disease prognosis." (PMID 35743565, 2022). "Elevated blood urea nitrogen (BUN) and reduced albumin have been prominently correlated with unfavorable outcomes in patients with cardiovascular diseases." (PMID 35600476, 2022). "After stepwise multivariate analysis, the only variables that remained associated significantly with risk of cardiovascular disease (hsCRP > 1 mg/L) were age, FBG, BUN, calcium, albumin, potassium, and statin use." (PMID 35300754, 2022). "Some (132, 23.8%) patients (group D) initiated PD with low albumin and high globulin and were more likely to be older, with a higher prevalence of DM and cardiovascular disease." (PMID 35889807, 2022). "Increasing age, the presence of cardiovascular disease and NLR ≥ 3.5 and higher PTH level were independently associated with serum albumin < 38 g/L." (PMID 36176632, 2022). "On the contrary, patients with high albumin and low globulin (group A) were more likely to be younger, with a lower prevalence of DM and cardiovascular disease." (PMID 35889807, 2022). "Additional variables that were independently associated with fracture risk after accounting for traditional osteoporotic factors included Asian race, lower serum albumin, use of a vitamin D therapy, HbA1c, and a history of cardiovascular disease." (PMID 35677742, 2022). "In order to alleviate these confounding factors, the participants were majorly recruited from northern Taiwan; Zn and renal outcomes were analyzed through adjustment for age, gender, albumin, eGFR, cardiovascular disease and other comorbidities." (PMID 35893916, 2022).